SFRP1 (secreted frizzled related protein 1)
Diseases named in the same sentence as SFRP1 in open-access papers (continued):
Sharing a sentence is not in itself a finding about the gene and the disease.
renal carcinoma (8 papers, 2012 to 2025). A carcinoma arising from the epithelium of the renal parenchyma or the renal pelvis. "Furthermore, SFRP1 DNA methylation was reported to accumulate with age in normal-appearing kidney tissues and be associated with increased renal cancer risk, which indicates the importance of SFRP1 in cancer." (PMID 29371858, 2018). "Other studies reported that sFRP-1 expression loss is a common event in renal cancer." (PMID 22325146, 2012). "Loss of sFRP-1 due to hypermethylation is common in renal carcinoma than other cancers." (PMID 22325146, 2012). "The methylation levels of six Wnt antagonist genes (sFRP-1, sFRP-2, sFRP-4, sFRP-5, Wif-1, and Dkk-3) were significantly higher in renal cancer compared to normal renal tissues." (PMID 22325146, 2012). "The authors showed that the invasive capability of a metastatic renal cancer cell line was decreased by attenuating sFRP1 with a concomitant decrease in the levels of metastasis related gene MMP10." (PMID 22325146, 2012). "SFRP1 and SFRP2 have shown oncogenic potential by increasing cellular proliferation or invasion and promoting in vivo tumor growth in renal cancer." (PMID 34205081, 2021). "MiR-1260b binds to the 3′ untranslated regions (UTRs) of the DKK2, secreted frizzled-related protein 1 (sFRP1) and SMAD family member 4 (Smad4) mRNAs, thereby down-regulating their expression in renal cancer cells." (PMID 26656471, 2015). "Overexpression of SFRP1 and SFRP3 has been detected in advanced renal cancer cells." (PMID 23825088, 2013).
esophageal adenocarcinoma (7 papers, 2008 to 2025). A malignant tumor with glandular differentiation arising predominantly from Barrett mucosa in the lower third of the esophagus. "In addition to that, a promotor methylation of the Wnt antagonist secreted frizzled receptor protein 1 (SFRP1), which is associated with a loss of function of SFRP1, was found in Barrett’s esophagus and EAC more often than in normal squamous mucosa." (PMID 30841855, 2019). "Solute SFRP1 proteins should be designed for cancers with SFRP1 as a good predictor, including pancreatic and esophageal adenocarcinoma." (PMID 32764696, 2020). "However, the methylation and downregulation of SFRP4 were less common than SFRP1, 2 and 5 genes in colorectal tumor, though they were both high in mesothelioma and esophageal adenocarcinoma." (PMID 38993819, 2024).
prostate tumor (7 papers, 2009 to 2025). "This shows that prostate tumour stroma SFRP1 signalling transmits growth signals to adjacent epithelial cells." (PMID 36968194, 2023). "It has been identified that SFRP1 is overexpressed in the stromal cells of the prostate tumour." (PMID 36968194, 2023).
cholangiocarcinoma (6 papers, 2016 to 2023). A carcinoma that arises from the intrahepatic biliary tree (intrahepatic cholangiocarcinoma) or from the junction, or adjacent to the junction, of the right and left hepatic ducts (hilar cholangiocarcinoma). "Our previous study demonstrated that SFRP1 regulates the occurrence and development of cholangiocarcinoma." (PMID 36368958, 2022). "Low methylation of SFRP1 (high expression of SFRP1) showed a trend of correlation with better prognosis in patients with pancreatic adenocarcinoma and cholangiocarcinoma." (PMID 32764696, 2020). "In the present study, we found that downregulation of HP1α suppresses cholangiocarcinoma proliferation through restoration of SFRP1 expression." (PMID 27385214, 2016). "Accordingly, in Cholangiocarcinoma (CCA) was declared that the overexpression and translocation of Dicer to the nucleus and formation complex with heterochromatin protein 1α (HP1α) leads to hypermethylation of SFRP1 promoter and suppression of its transcription through recruiting Dnmts." (PMID 33632341, 2021).
colorectal tumor (6 papers, 2006 to 2024). "The importance of SFRP5 as a regulatory site in an epigenetic mechanism was recently shown with the demonstration that methylation and repression of the promoters for SFRP1, −2, −4, and −5 in colorectal tumor cells causes constitutive expression of Wnt signaling and enhances tumor promotion." (PMID 16733553, 2006).
meningioma (6 papers, 2015 to 2023). A generally slow growing tumor attached to the dura mater. "A strong up-regulation of secreted frizzled-related protein 1 (SFRP1) expression was suggested in all meningiomas with AKT1E17K mutation." (PMID 27429002, 2016). "SFRP-1 for instance, has been shown to be upregulated in AKT1(E17K) activating mutation which predominantly appears in WHO 1 meningiomas." (PMID 38023177, 2023). "It has been shown that Secreted Frizzled-Related Protein 1 (SFRP1), a member of a family of soluble proteins known for their ability to inhibit the Wnt signalling pathway plays a role in meningioma recurrence." (PMID 27429002, 2016). "The validation of the microarray expression data for SFRP1 confirmed significantly lower mRNA levels in recurrences than in original meningiomas (p < 0.05)." (PMID 27429002, 2016). "For this purpose, 44 WHO grade I meningiomas, including 8 showing regrowth after radiosurgery, were analysed for Ki-67 and NDRG4 protein expression, loss of 1p36 and promotor hypermethylation of the genes NDRG1-4, SFRP1, HOXA9 and MGMT." (PMID 34385566, 2021). "SFRP1 has been previously identified as underexpressed in human meningiomas." (PMID 29073243, 2017). "MSP for NDRG1-4, SFRP1, HOXA9 and MGMT was performed on 41 meningioma samples and 10 nontumoral control brain tissue samples." (PMID 34385566, 2021).
non-small cell lung carcinoma (6 papers, 2007 to 2024). A group of at least three distinct histological types of lung cancer, including non-small cell squamous cell carcinoma, adenocarcinoma, and large cell carcinoma. "In non-small cell lung cancer (NSCLC), for instance, the epigenetic silencing of SFRP1 is associated with lymph node metastasis and disease progression within a year after surgery." (PMID 37369946, 2023). "Using non-small-cell lung carcinoma cells in which SFRP1 was methylated, they showed that when SFRP1 was cotransfected with mutant β-catenin, SFRP1 could attenuate TCF/LEF activity induced by exogenous β-catenin." (PMID 18283316, 2008). "Since EMT is well known as a classic cell phenotype that is frequently involved in the regulation of cancer cell progression, we hypothesized that LINC01089 suppressed non-small cell lung carcinoma EMT progression by sponging miR-27a to target the SFRP1-Wnt/β-catenin pathway." (PMID 33282723, 2020). "Functionally, LINC01089 acts as a miR-27a sponge by elevating SFRP1 expression and modulating the Wnt/β-catenin–EMT pathway to arrest non-small cell lung carcinoma tumorigenesis." (PMID 33282723, 2020).
colorectal adenoma (5 papers, 2006 to 2020). An adenoma that arises from the colon or rectum. "According to Q-score values used for semiquantitative immunohistochemistry analysis, the overall SFRP1 protein expression decreased along the colorectal adenoma-carcinoma sequence." (PMID 26482433, 2015). "That sFRP1 is hypermethylated in both of these lesions lends weight to the hypothesis that ACFs are indeed precursors of large bowel adenomas." (PMID 16523202, 2006). "We investigated the capacity of β-catenin to regulate sFRP1 transcription in a normal intestinal epithelial cell line and measured its relative expression and methylation in premalignant colorectal adenomas, the earliest stage of tumorigenesis where expression can be measured reliably." (PMID 16523202, 2006). "We have shown that sFRP1 transcription can be driven by β-catenin in normal intestinal epithelial cells, but that premalignant colorectal adenomas contain greatly reduced levels of sFRP1 compared to matched normal mucosa and this is accompanied by increased methylation at the sFRP1 locus." (PMID 16523202, 2006). "sFRP1 protein expression and cellular distribution were analysed in a series of formalin-fixed wax-embedded sections taken from seven non-neoplastic large bowel mucosa samples and 22 left sided colorectal adenomas." (PMID 16523202, 2006).
heart failure (5 papers, 2016 to 2026). Inability of the heart to pump blood at an adequate rate to meet tissue metabolic requirements. "In animal models, secreted frizzled related protein 1 (Sfrp1) inhibition of the Wnt signaling pathway is beneficial because Sfrp1 reduces myocardial apoptosis and prevents heart failure." (PMID 27048460, 2016). "Transcript levels of several established biomarkers, including Spp1, Sfrp1, Sfrp2, Tnc, Vim, Mmp9, and Tnfrsf1a, and several inflammatory markers that are known to be activated in heart failure, such as Cd44, Cd83, Ccl7, Irf7, and Nr4a2, were upregulated in the Myh6-McmTamDspfl/fl cardiomyocytes." (PMID 40608429, 2025).
invasive ductal breast carcinoma (5 papers, 2009 to 2023). The most common type of invasive breast carcinoma, accounting for approximately 70% of breast carcinomas. "Therefore, we examined the methylation status of RASSF1A and SFRP1 in DNA isolated from 12 invasive ductal breast carcinomas (IDC), seven normal breast tissues, and three vHMEC populations isolated from disease-free reduction mammoplasties." (PMID 19995452, 2009). "Similarly, in a comparison of FFPE-sections from human invasive ductal carcinoma (IDC) with ductal carcinoma in situ (DCIS) or morphologically normal control tissue, Sfrp1 mRNA expression was significantly reduced in IDC." (PMID 37402051, 2023).
pancreatic adenocarcinoma (5 papers, 2016 to 2023). "This study examined the association of SFRP1 promoter hypermethylation with efficiency of Gem chemotherapy in patients with stage IV pancreatic adenocarcinoma." (PMID 34830873, 2021). "SFRP1 expression was relatively lower in ampullary adenocarcinoma than in pancreatic adenocarcinoma." (PMID 32764696, 2020). "High expression levels of SFRP1 predicts poor prognosis in patients with gastric adenocarcinoma but represents better survival of patients with pancreatic adenocarcinoma." (PMID 32764696, 2020). "Hypermethylation of SFRP1, BNC1, and TFPI2 were in the univariate screening associated with poor survival for stage IV pancreatic adenocarcinoma." (PMID 29212200, 2017). "Initially, analysis of pancreatic adenocarcinoma TCGA data confirmed that the methylation levels of BMP3, NPTX2, SPARC, SFRP1 and TFPI2 genes were significantly higher in tumor compared with normal tissue, reinforcing their potential as useful biomarkers." (PMID 37481552, 2023). "We developed a diagnostic prediction model (age >65, BMP3, RASSF1A, BNC1, MESTv2, TFPI2, APC, SFRP1 and SFRP2), which was able to differentiate between pancreatic adenocarcinoma and a large control group of great clinical relevance." (PMID 27891190, 2016). "A panel of hypermethylated genes (BMP3, RASSF1A, BNC1, MESTv2, TFPI2, APC, SFRP1 and SFRP2) are able to differentiate between patients with pancreatic adenocarcinoma and a most relevant control group." (PMID 27891190, 2016). "A prognostic value of SFRP1 hypermethylation has, to our knowledge, not previously been described regarding pancreatic adenocarcinoma." (PMID 29212200, 2017).
pulmonary fibrosis (5 papers, 2014 to 2026). Chronic progressive interstitial lung disorder characterized by the replacement of the lung tissue by connective tissue, leading to progressive dyspnea, respiratory failure, or right heart failure. "EVs from BAL have been implicated in pulmonary fibrosis, with SFRP1‐enriched EVs exacerbating disease progression." (PMID 41541657, 2026). "Sfrp1 deficiency inhibited the activity of fibroblast-derived EVs to potentiate lung fibrosis in vivo." (PMID 39315549, 2024). "This apparent contradiction with SFRP1's previously suggested antifibrotic role underscores the need for a more comprehensive analysis of its function in pulmonary fibrosis." (PMID 41541657, 2026). "Treatment with demethylating agents such as 5‐azacytidine restored SFRP1 expression and exerted antifibrotic effects in pulmonary fibrosis and SSc models." (PMID 41541657, 2026). "Based on these in vitro observations and the expression profile during bleomycin-induced lung fibrosis, we further studied the role of endogenous SFRP1 and FRZB using the respective knockout mice compared to wild-type (WT) littermates." (PMID 25317206, 2014). "We show that both Sfrp1 and Frzb are upregulated during the course of bleomycin-induced lung fibrosis." (PMID 25317206, 2014). "In pulmonary fibrosis, hypermethylation‐induced silencing of SFRP1 correlates with increased disease severity, while treatment with a DNA methyltransferase inhibitor 5‐aza‐2′‐deoxycytidine (5‐aza) restores their expression and improves lung function, suggesting a protective role for SFRP1." (PMID 41541657, 2026). "Moreover, a recent study employing longitudinal single-cell and lineage-tracing experiments identified secreted frizzled-related protein 1 (SFRP1) as a key modulator of TGF-β1-driven fibroblast to myofibroblast differentiation in pulmonary fibrosis." (PMID 38891078, 2024). "During the course of bleomycin-induced lung fibrosis, Sfrp1 and Frzb expression are upregulated." (PMID 25317206, 2014). "We therefore studied the effect of SFRPs on lung fibrosis in in vitro and in vivo models, including the effect caused by absence of endogenous SFRP1 and FRZB in the bleomycin-induced lung fibrosis model." (PMID 25317206, 2014). "Here, we studied the role of two extracellular Wnt antagonists, secreted frizzled-related protein-1 (SFRP1) and frizzled-related protein (FRZB) on lung fibrosis in vitro and in vivo." (PMID 25317206, 2014). "Further evidence for active WNT signaling in lung fibrosis came from microarray analysis of IPF lungs, confirming enrichment of WNT-related genes encompassing ligands (WNT2, WNT5a), receptors (FZ7, FZ10), antagonists (SFRP1), and target genes (LEF1)." (PMID 25317206, 2014).
renal cell carcinoma (5 papers, 2018 to 2023). "In addition, miR-1260b, highly expressed in renal cell carcinoma, promoted cellular proliferation and invasion via the reduction of the expression of several tumor suppressor genes associated with Wnt signaling, such as sFRP1, Smad4, and Dkk263." (PMID 32523124, 2020). "Similar to these results, a Croatian study found that over 30% of renal cell carcinoma samples had higher SFRP1 protein levels compared to adjected normal tissues." (PMID 37999144, 2023). "SFRP1 and FOLR1 have a greater association with urologic tumors, like renal cell carcinoma or kidney cancer." (PMID 35719392, 2022).
amyloid (4 papers, 2020 to 2025). "Notably, key ECM-associated proteins such as SMOC1, MDK, and SFRP1 are recurrently elevated and exhibit strong specificity to amyloid pathology, spanning both parenchymal plaques and vascular amyloid in CAA." (PMID 41282800, 2025).
bladder tumor (4 papers, 2009 to 2023). "miR-1-3p can limit the proliferation of J82 cells via the upregulation of SFRP1, which is down-regulated in bladder tumor tissue." (PMID 36185280, 2022). "The methylation levels of sFRP-2 and Dkk-3 were found to be significant independent predictors of bladder tumors, whereas with sFRP-1, sFRP-5, and Wif-1, a trend towards significance was found as independent predictors." (PMID 22325146, 2012). "Another study demonstrated higher promoter CpG hypermethylation and lower expression of mRNA transcripts for sFRP-1, sFRP-2, sFRP-4, and sFRP-5, Dkk-3, and Wif-1 genes in bladder tumor compared with normal bladder mucosa showing an inverse correlation." (PMID 22325146, 2012).
dysplasia (4 papers, 2006 to 2025). A usually neoplastic transformation of the cell, associated with altered architectural tissue patterns. "Real-time RT–PCR analysis showed a reduction in sFRP1 expression in all 12 dysplastic lesions (median 485-fold, IQR 120- to 1500-fold), indicating factors other than β-catenin influence sFRP1 levels." (PMID 16523202, 2006).
emphysema (4 papers, 2011 to 2025). "Already studies have shown that the Wnt/ β-catenin pathway attenuates experimental emphysema and the Wnt inhibitor SFRP-1 up regulates the expression of proteases that are important in the development of human emphysema." (PMID 23626909, 2012). "Interestingly, SFRP1, another member of the SFRP family, is up-regulated in the distal epithelial cells of the mouse lung during development and in murine emphysema models." (PMID 21490961, 2011).
endometrial cancer (4 papers, 2012 to 2025). Primary or metastatic malignant neoplasm involving the endometrium (mucous membrane that lines the endometrial cavity). "Regarding field cancerization, methylation of hMLH1, CDKN2A/P16 and SFRP1 has been recently indicated to be associated with malignant transition in endometrial cancer." (PMID 25405986, 2014). "Consistent (1.8–7.2-fold) treatment-induced upregulation of SFRP1 was seen in HCT15, HCT116, and HEC59 analogous to LS-associated CRC and endometrial cancer." (PMID 26203307, 2015). "A relationship between down-regulation of SFRP1 and SFRP4 and microsatellite instability is known for endometrial cancers." (PMID 22363760, 2012).
keloid (4 papers, 2015 to 2025). An irregularly shaped, elevated mark on the skin caused by deposits of excessive amounts of collagen during wound healing. "Promoter methylation and reduced expression of SFRP1 are observed in keloids and cutaneous squamous cell carcinoma." (PMID 40319033, 2025). "For instance, keloid fibroblasts exhibited reduced levels of histone acetylation in the secreted frizzled-related protein 1 (SFRP1), resulting in upregulation of the Wnt (Wingless; Int1) signaling pathway and subsequently promoting keloid formation." (PMID 38338767, 2024).
lung adenocarcinoma (4 papers, 2011 to 2023). A carcinoma that arises from the lung and is characterized by the presence of malignant glandular epithelial cells. "The silencing of SFRP1 is especially of interest since the WNT pathway was recently implicated in lung adenocarcinoma metastasis." (PMID 21731750, 2011).
mesothelioma (4 papers, 2007 to 2025). A usually malignant and aggressive neoplasm of the mesothelium which is often associated with exposure to asbestos. "A meta‐analysis has further revealed that the APC gene is significantly hypomethylated in mesothelioma, while CDH1, ESR1, miR‐34b/c, PGR, RARβ, SFRP1, and WIF1 are significantly hypermethylated." (PMID 40904706, 2025). "A recent systematic review and quantitative meta-analysis of DNA methylation in mesothelioma found both significantly hypomethylated genes (APC) and hypermethylated genes (CDH1, ESR1, miR34b/c, PGR, RATO, SFRP1, and WIF1)." (PMID 38297314, 2024).
ocular hypertension (4 papers, 2015 to 2019). Abnormally high intraocular pressure. "It is possible that a feedback system exists, such that SFRP1 induces ocular hypertension, but high IOP reduces SFRP1 expression." (PMID 31382918, 2019). "Our in vivo study showed that K-cadherin significantly decreased sFRP1-induced ocular hypertension (P < 0.05, n = 6)." (PMID 29625468, 2018). "Also, adenovirus-mediated sFRP1 expression elicits ocular hypertension in mice." (PMID 31318361, 2019).
osteosarcoma (4 papers, 2020 to 2025). A usually aggressive malignant bone-forming mesenchymal neoplasm, predominantly affecting adolescents and young adults. "Knockout of SFRP1 reduced apoptosis of U2-OS human osteosarcoma cells by approximately 50% and increased the mineral attachment rate of bone trabeculae by approximately 30%." (PMID 39606935, 2025). "Another study demonstrated that the SFRP1 inhibitor diarylsulfonylsulfonamide can stimulate the Wnt/β-catenin signaling pathway by inhibiting the expression of SFRP1 in U2-OS human osteosarcoma cells." (PMID 39606935, 2025). "This study also demonstrated that knockdown of miR-27a induced the upregulation of SFRP1 and suppressed the cell proliferation and invasion in osteosarcoma cell lines." (PMID 32074995, 2020). "Moreover, it has been discovered that miR-27a can promote the proliferation and invasion of osteosarcoma via the SFRP1-dependent Wnt/β-catenin signaling pathway." (PMID 38309281, 2023).